FLG (filaggrin)
Diseases named in the same sentence as FLG in open-access papers (continued):
Sharing a sentence is not in itself a finding about the gene and the disease.
dermatitis (66 papers, 2011 to 2026). An inflammatory process affecting the skin. "Filaggrin, an intracellular component of the SC, is assumed to be critical for normal cornification, as filaggrin-deficient mice exhibit reduced SC barrier function and spontaneous AD-like dermatitis." (PMID 35834333, 2022). "Filaggrin expression has been reported to be reduced in AD, and filaggrin mutations have been reported to cause skin inflammation, causing skin barrier damage in AD and promoting IgE sensitization through the damaged skin barrier." (PMID 32063982, 2020). "Filaggrin mutation in mice results in spontaneous skin inflammation and increases in the ILC2 population, IL-1β production, and other cytokines related to AD in skin." (PMID 32326002, 2020). "FLG mutations have also been associated with other skin disorders, such as ichthyosis vulgaris, occupational contact dermatitis, and chronic hand eczema." (PMID 32054030, 2020). "An FLG-deficient mouse model showed spontaneous dermatitis with impaired skin barrier and delayed skin barrier recovery from irritation." (PMID 29316698, 2018). "We now show that filaggrin-deficient mice, analogous to FLG mutations in human subjects, have spontaneous dermatitis, become atopic and progress to lung inflammation with age." (PMID 26299987, 2016). "In sum, our study reveals that filaggrin deficiency in the appropriate genetic background leads to spontaneous dermatitis associated with increased IL1β, Th2-related cytokines and activated NFκB signalling." (PMID 23844115, 2013). "Our data suggest that FLG null mutations, the cause of ichthyosis vulgaris, are associated with dermatitis at “exposed areas”, especially the cheeks and the back of the hands, but also the feet and extensor areas." (PMID 23166590, 2012). "We found that canonical Notch signaling is required for late-stage epidermal differentiation and correct processing of filaggrin, a process when perturbed being closely associated with barrier function defects and skin disorders." (PMID 21267458, 2011). "Truncated profilaggrin/filaggrin flaky tail mutant form, also identified in the 60-min HI-affected eye lavage EVs, is associated with a defective skin barrier and various skin conditions, including ichthyosis and dermatitis." (PMID 41488750, 2025). "Mice with a frameshift mutation in the filaggrin gene develop spontaneous dermatitis." (PMID 30937919, 2019). "Transgenic expression of IL-33 in murine skin causes spontaneous dermatitis to develop and, in humans, may modulate filaggrin expression and thus skin barrier function." (PMID 29378633, 2018). "Immunosuppressed mice with cutaneous deficiency in both STAT3 and filaggrin displayed rapidly progressing vaccinia disease, characterized by elevated local virus recovery, dermatitis, mucosal mast cell accumulation, and activin A overexpression in infected skin." (PMID 28081250, 2017). "Importantly, nILC2 numbers are also specifically increased in the skin of Rag1−/−Flgft/ft mice, indicating the importance of ILC2s in the pathogenesis of skin inflammation arising from skin barrier dysregulation caused by filaggrin deficiency." (PMID 26299987, 2016). "Additionally, two groups demonstrated that homozygous mutation of TMEM79 is responsible for the spontaneous dermatitis phenotype in flaky tail mice which was originally thought caused solely by FLG mutations." (PMID 27777593, 2016). "In this study of at-risk children with AD, we find that the FLG null defines an endotype characterized by dermatitis with a predilection site at exposed areas of the body, in particular hands and cheeks, and an up-regulation in both acute and chronic morphological markers." (PMID 23166590, 2012). "The treatment also enhanced the expression of skin barrier proteins, including filaggrin and involucrin, and reduced serum IgE levels and T helper 2-associated cytokines, indicating its potential as a functional food for managing pollution-induced skin disorders." (PMID 39857357, 2024).
dermatitis (continued). "In murine models of AD, FLG deficiency alters both the intracellular and extracellular architecture of keratinocytes, interferes with lipid secretion, reduces inflammatory thresholds to irritants and haptens, permits increased allergen penetration and enhances skin inflammation." (PMID 34198894, 2021). "Therefore filaggrin deficiency leads to a defective skin barrier, with subclinical cutaneous inflammation in nonlesional skin, and is accompanied by a lower threshold for skin inflammation after exposure to hapten." (PMID 26299987, 2016). "Topical application of 1% K-7-G significantly alleviated AD-like symptoms in a mouse model, decreasing dorsal skin thickness, dermatitis score, and scratching frequency while restoring the expression of filaggrin, loricrin, and occludin (p < 0.0001)." (PMID 42075836, 2026). "PP reduced dermatitis severity, lowered IgE levels, decreased mast cell infiltration, modulated Th2 cytokines, restored filaggrin levels." (PMID 40282735, 2025). "Random-effects models pooled standardized mean differences (SMDs) with 95% confidence intervals (CIs) for primary outcomes (dermatitis severity and scratching behavior) and secondary outcomes (cytokines, epidermal thickness, and filaggrin (FLG))." (PMID 41560747, 2025). "The efficacy of the compound was confirmed using dermatitis scores, ear thickness measurements, serum IgE levels, histological analysis of lesions, and filaggrin expression analysis, which is important for barrier function." (PMID 38713650, 2024). "After topical 2,4-dinitrochlorobenzene (DNCB) treatment, Stat3 cKO mice developed worsened AD-like skin inflammation with increased Ki67+ cells, decreased filaggrin and loricrin expression, and downregulated S100A9 and LL37." (PMID 38053996, 2023). "Since Th2 cytokines impact keratinocyte differentiation and hamper the expression of FLG through JAK-STAT signaling, JAK inhibitors potently upregulate FLG expression, restore skin barrier function and reduce skin inflammation." (PMID 36904070, 2023). "Topical application of a high concentration of glucose has been suggested to reduce skin inflammation and induce cldn-1 and filaggrin expression in inflamed skin." (PMID 36836073, 2023). "We also investigated the effects of the topical application of an ERK inhibitor on the dermatitis score, transepidermal water loss (TEWL), histological change, and expression of filaggrin, using an AD-like NC/Nga murine model." (PMID 35408826, 2022). "Unfortunately, flaky tail mice also carry a spontaneous mutation in the Transmembrane Protein 79/Matt gene (Tmem79) and exhibit AD-like dermatitis, which precludes conclusions on the role of filaggrin based on this model." (PMID 35628125, 2022). "Reduced levels of FLG and LOR expressions are associated with barrier disruption and skin inflammation, weakening of the epidermal barrier function, and are also observed in inflamed skin." (PMID 35268661, 2022). "Filaggrin mutation leads to loss of skin barrier function and an increase in the ILC2 population, promoting acute skin inflammation and the development of AD." (PMID 32326002, 2020). "IL-1β and IL-1R1 signaling plays a critical role in chronic dermatitis inflammation in Filaggrin-mutant mice because anti-IL-1β antibody treatment alleviated dermatitis symptoms." (PMID 32326002, 2020). "The published literature focusing on Filaggrin is mainly restricted to a skin condition known as dermatosis." (PMID 31884678, 2020). "This phenomenon was observed in dermatitis mice model and was found to be exclusive from filaggrin abnormality." (PMID 31360714, 2019). "Filaggrin‐mutant (Flgft/ft) mice develop spontaneous skin inflammation accompanied by an increase in skin ILC2 numbers, IL‐1β production, and other cytokines recapitulating human AD." (PMID 30937919, 2019). "Abnormalities in filaggrin, other stratum corneum constituents, and tight junctions induce and/or promote skin inflammation." (PMID 29259713, 2017).
dermatitis (continued). "By inhibiting type 2 cytokine signaling, dupilumab markedly improves dermatitis manifestations and restores epidermal barrier function through increased expression of filaggrin and tight-junction proteins, leading to reduced transepidermal water loss and enhanced activity of antimicrobial peptides." (PMID 41357247, 2025). "Notably, filaggrin is a major protein in maintaining the normal function of the epidermal barrier, and the lack or dysfunction of filaggrin can result in a range of skin disorders." (PMID 37809065, 2023). "Vernodalin isolated from Vernonia amygdalina increase filaggrin (FLG) mRNA expression levels and reduce IL-33mRNA expression in mice (vs. control group) also significantly reduce the dermatitis score (vs. control) in regard to ear skin lesions at 100 μg/ml via topical administration." (PMID 35498985, 2022). "More importantly, in a murine AD-like model, TJ proteins were suppressed in skin inflammation but not directly affected by filaggrin deficiency." (PMID 35834333, 2022). "In addition, oral administration of JTC-801 promoted protein level of FLG and suppressed the development of AD-like skin inflammation in NC/Nga mice." (PMID 34198894, 2021). "Another perspective about FLG that makes this work meaningful, other than considering it just as a treatment of skin disorder, is that FLG is one of the many types of tandem repeat proteins that have a greater chance of mutation, which can render them dysfunctional." (PMID 33195157, 2020). "Immunosuppressed, filaggrin-deficient mice, treated with the topical STAT3 inhibitor Stattic® prior to ACAM-2000 infection, demonstrated rapid weight loss, prolonged vaccinia burden in skin, and dermatitis." (PMID 28081250, 2017). "Links between skin inflammation, protease/inhibitor balance, filaggrin processing, the composition and molecular arrangement of the extracellular lipid matrix, corneodesmosome-degradation–dependent desquamation and SC barrier function do indeed exist and should be further investigated." (PMID 25378284, 2015). "Loss-of-function mutations in the gene encoding filaggrin (FLG) are a highly significant risk factor for atopic disease, but the molecular mechanisms leading to dermatitis remain unclear." (PMID 24880632, 2014). "Other mechanisms, rather than primary barrier abnormality, might be responsible for the FLG wild type children’s dermatitis." (PMID 23166590, 2012). "Increased IL1β production during skin inflammation reduces the expression of filaggrin, a protein essential for skin barrier function, which suggests that the down-regulation of filaggrin might be related to increased transepidermal water loss and increased permeability to allergens." (PMID 39199350, 2024). "It is interesting that we could partly confirm this finding in our cohort of children, as FLG null carriers mainly had chronic markers of dermatitis on the back of their hands, whereas acute markers were upregulated in the palms as well as the back of the hands." (PMID 23166590, 2012). "Thus, filaggrin deficiency in vivo might lead to subclinical skin inflammation via Langerhans cell activation rather than via upregulation of pro-inflammatory cytokines in KCs." (PMID 35628125, 2022). "All these pathways suggest a crucial role of the skin flora in triggering AD lesions, suggesting that specific subpopulations of microbes present in the most affected sites of this dermatosis could be the cause of the lesions, rather than the classical theory of filaggrin loss in flexural areas." (PMID 34944487, 2021). "In addition, the expression level of filaggrin was reduced by C3A and GGRT treatment, and the expression levels of dermatitis-related proteins, including KLK7, PAR-2, TSLP, and IL-4, were markedly recovered." (PMID 34946332, 2021).
dermatitis (continued). "One of these, miR-155-5p, when blocked, leads to a higher production of filaggrin, lesser production of TSLP and IL-33, which is another interleukin involved in this form of dermatosis, and a strengthening of tight junctions among cells via upregulation of occludin." (PMID 34944487, 2021). "A recent report from Croatia revealed that loss-of-function mutation of FLG was detected in only 4 of 91 AD patients and none of 47 non-AD controls; it also showed that elevated TEWL is associated with skin inflammation but not with FLG mutation." (PMID 33233866, 2020). "Filaggrin mutant mice significantly differ in their microbiome composition compared to wild type mice and do not develop skin inflammation under germ-free conditions prompting a crucial role for the microbiome in shaping this setting." (PMID 31781103, 2019). "As a secondary finding we showed that FLG null children had more severe dermatitis, characterized by a higher number of visits in the clinical research unit, a more generalized dermatitis and a non-significant trend of higher SCORAD value." (PMID 23166590, 2012). "Indeed, SSA ameliorates AD-like skin inflammation by reducing EGR1-mediated TSLP expression in HaCaT keratinocytes; however, the effect of SSA on the expression of FLG remains unclear." (PMID 39274912, 2024). "The protective effects of PF and PW on UVB-induced skin inflammation and skin barrier damage in human immortalised epidermal keratinocytes (HaCaT) cells (including cell viability, ROS, HO-1, NQO1, IL-1β, IL-8, TNF-α, KLK-7, FLG, AQP3 and Caspase 14 levels) are investigated." (PMID 36771204, 2023). "Of note, the differential DNAm in the genomic region of the filaggrin gene (FLG), which plays an important role in the pathogenesis of atopic dermatitis and allergic disease, is identified in our comparison analysis between nonatopic dermatitis and atopic dermatitis participants." (PMID 33571165, 2021).
allergic disease (47 papers, 2008 to 2025). An immune response that occurs following re-exposure to an innocuous antigen, and that requires the presence of existing antibodies against that antigen. "Mice with FLG mutations have also been commonly used to understand the role of this protein in allergic disease." (PMID 39066790, 2024). "There is an IgE-high, extrinsic subtype (with frequent filaggrin mutations), showing allergy to proteins and food allergy, and an IgE-normal, intrinsic subtype, showing allergy to metals." (PMID 39195286, 2024). "Risk factors for AD include filaggrin (FLG) gene mutations and a family history of atopic or allergic disease." (PMID 38279315, 2024). "The FLG gene encodes for pro-filaggrin, that is a major constituent of the epidermis, polymorphisms in which are associated with skin and allergic diseases." (PMID 37456561, 2023). "There has been a growing body of evidence that mutations with loss-of-function in FLG are strong risk factors for AD and allergic diseases, and FLG expression is significantly reduced in AD patients, even without FLG mutations." (PMID 36362286, 2022). "Loss-of-function mutations in genes encoding the skin component filaggrin are related to a disrupted skin barrier, are often seen in children with AD, and are associated with IgE sensitization and allergy to foods in general, and peanut specifically." (PMID 35386994, 2021). "Mutations in the filaggrin gene increase the incidence of various allergic diseases, including epidermal barrier defects and increased skin infections." (PMID 32699202, 2020). "We aimed to detect genetic associations of CMA using reported single nucleotide polymorphisms (SNP) in other allergic diseases and genetic mutations within the filaggrin (FLG) gene." (PMID 26941931, 2015). "Earlier reports involving allergic diseases have shown that a defective FLG-gene was involved, albeit the prevalence of these mutations is ethnicity specific." (PMID 26941931, 2015). "Filaggrin is a key natural moisturizing factor that maintains the ability to regulate the skin moisture barrier, while the mutation of the filaggrin gene resulted in skin losing water to allow the entrance of bacteria, leading to allergies, irritation and infection." (PMID 30101144, 2018). "Finally, the genetic component of the epidermal barrier dysfunction hypothesis, maybe due to FLG‐null mutation, could support our finding that paternal history of allergic disease is a risk factor for ES." (PMID 29516688, 2018). "Allergic diseases have a strong genetic component, and recent findings that the filaggrin mutation may be a risk factor for the development of peanut allergy marks a significant step toward understanding the full picture of the etiology of allergy." (PMID 24735755, 2014). "Although the importance of TSLP in the pathogenesis of allergic diseases is widely recognised, little is currently known about the direct interplay between TSLP, filaggrin-deficient skin and naïve CD4+ T cells in humans." (PMID 28377574, 2017). "Currently, it is unknown whether filaggrin is important in equine allergies, whether any difference in expression exists between normal and allergic horses, or whether changes are secondary to inflammation or a signature of disease." (PMID 40005851, 2025). "For example, filaggrin (FLG) is a general food allergy risk gene, HLA has food-specific effects, and mucosa-associated lymphoid tissue lymphoma translocation 1 (MALT1) variants increase the risk of sensitization and the development of allergy." (PMID 39493746, 2024). "Although it is known that Der p 38 has a direct cleavage activity on filaggrin, Der p 38 may also facilitate the infiltration of other allergens, thereby resulting in the development and aggravation of allergy by protease activity." (PMID 34691014, 2021). "Filaggrin (Filament Aggregating Protein—FLG) is a prominent epidermal protein that plays a pivotal role in the pathogenesis of AD and allergic diseases." (PMID 41440493, 2025).
allergic disease (continued). "However, allergic sensitization may be facilitated in the presence of intrinsic barrier defects, as evidenced in genetic studies showing the significant association of filaggrin (FLG) loss-of-function mutants, impaired skin barrier function, and the development of allergic disease." (PMID 34068047, 2021). "Thus, it is important to keep hypoxia in epithelial tissues to avoid the onset and exacerbation of allergy via downregulating TSLP and enhancing filaggrin expressions." (PMID 31682627, 2019).